UNC5C (unc-5 netrin receptor C)
Diseases named in the same sentence as UNC5C in open-access papers (continued):
Sharing a sentence is not in itself a finding about the gene and the disease.
Ataxia (1 paper, 2025). Ataxia refers to impaired coordination of voluntary muscle movement. "Previous studies using Unc5c knockout mice have reported that Unc5c is widely expressed in neurons in the precerebellar and deep cerebellar neurons, leading to neurodevelopmental defects, such as cerebellar hypoplasia and ataxia." (PMID 40869954, 2025).
Brain atrophy (1 paper, 2025). Partial or complete wasting (loss) of brain tissue that was once present. "Therefore, it is imperative to understand the molecular underpinnings of the T835M mutation in UNC5C-related brain atrophy and neuronal cell death to inform the potential of UNC5C as a therapeutic target for AD." (PMID 40468412, 2025).
cognitive decline (1 paper, 2017). "Moreover, in our study, more rapid decline in episodic memory seemed to drive the association of the UNC5C allele rs3846455G with cognitive decline, and this is consistent with the suggested selective effect of UNC5C on hippocampus, a brain region critical for episodic memory." (PMID 28441426, 2017).
Cyanosis (1 paper, 2016). Bluish discoloration of the skin and mucosa due to poor circulation or inadequate oxygenation of arterial or capillary blood. "For example, in animals where Hox5 and Unc5c were mutated, a profound reduction of costal muscle innervation of the diaphragm, which leads to neonatal cyanosis, is observed." (PMID 27466379, 2016).
dementia (1 paper, 2025). Loss of intellectual abilities interfering with an individual's social and occupational functions. "Our findings also covered well-known dementia-associated proteins, such as BCAN, CNTN5, and NCAN, along with identifying recently promising biomarkers, including IL18, MMP12, TNFSF12, and UNC5C, where these biomarkers presented the highest protein importance in their clusters." (PMID 40748327, 2025).
epithelial ovarian cancer (1 paper, 2015). "Low BMPR2 expression and down-regulated UNC5C are associated with epithelial ovarian cancer." (PMID 25591662, 2015).
kidney cancer (1 paper, 2014). Primary or metastatic malignant neoplasm involving the kidney. "What’s more, we discovered that gene UNC5C is highly associated with kidney cancer and so on." (PMID 25285156, 2014). "We also investigate the 45 kidney genes with higher expression and find that gene UNC5C is highly related with kidney cancer." (PMID 25285156, 2014).
lung carcinoma (1 paper, 2021). "The expression of UNC5A, UNC5B, or UNC5C is down-regulated in multiple cancers including lung cancer, and UNC5B has also been indicated as a putative tumor suppressor." (PMID 33711952, 2021).
ovarian tumor (1 paper, 2015). "Because UNC5C is expressed in several bovine tissues, including the ovary, we used the murine ovarian tumor line OV2944-HM-1 to assess luciferase activity." (PMID 26147436, 2015).
preeclampsia (1 paper, 2025). Preeclampsia is a hypertensive disorder of pregnancy that is characterized by new-onset hypertension with proteinuria presenting after 20 weeks of gestation, and depending on mild or severe forms may initially present with severe headache, visual disturbances, and hyperreflexia. "Although late-onset preeclampsia is not as strongly associated with placental vascular dysfunction as early-onset preeclampsia, genes such as CP, IGFBP7, CDH13, ROBO1, UNC5C, NRXN3, and ITGA1 suggest subtle changes in angiogenic pathways." (PMID 41444673, 2025).
renal carcinoma (1 paper, 2025). A carcinoma arising from the epithelium of the renal parenchyma or the renal pelvis. "In general, NTN1, NEO1, DSCAM, UNC5C, and UNC5D are all regulated by HDAC members in renal cancer, suggesting that NTN1, NEO1, DSCAM, UNC5C, UNC5D, and especially NEO1 and UNC5C may be essential for the regulation and outcome of renal cancer." (PMID 41407823, 2025).
renal cell carcinoma (1 paper, 2025). "Differential expression of UNC5B and UNC5C was found in renal cell carcinoma (KIRC, KIRP, and KICH)." (PMID 41407823, 2025).
xerostomia (1 paper, 2025). Dryness of the mouth resulting from reduced salivary secretion. "The downregulation of Unc-5 Netrin Receptor C (encoded by UNC5C) in the right parotid further implies neuronal regulation in xerostomia." (PMID 40806170, 2025). "The downregulation of key proteins involved in oxidative stress and neurodegenerative diseases, encoded by PARK7, GLO1, GLUD2, VDAC2, UQCRC1, and UNC5C, including the 20S proteasome core complex proteins, highlights a possible mechanistic link to xerostomia pathophysiology." (PMID 40806170, 2025).
tumor (17 papers, 2013 to 2024). "Furthermore, WES of MIBC tumor samples revealed that somatic mutations of UNC5C and DNA repair genes contributed to prolonged survival." (PMID 34239995, 2021). "UNC5C, identified as downregulated in CRC, acts as a tumor suppressor and is linked to tumor progression in colorectal malignancies." (PMID 39011483, 2024). "The potential of methylated UNC5C or UNC5D in circulating tumor DNA as biomarker for CRC should also be taken into consideration in future study." (PMID 34922605, 2021). "Numerous studies have provided ample evidence that UNC5C, a tumor suppressor, is down-regulated in a large fraction of colorectal malignancies, primarily through promoter methylation." (PMID 34922605, 2021). "Among the tumor suppressor genes frequently epigenetically downregulated in CRC, the four related genes of the UNC5 family: UNC5A, UNC5B, UNC5C and UNC5D encode dependence receptors that regulate the apoptosis/survival balance." (PMID 33126652, 2020). "Using allelic retention status in the HCC tumor as a criterion, three genes (UNC5C, DKK2, and ZGRF1) from the LOH region were evaluated for further investigation." (PMID 27203079, 2016). "The other netrin-1 receptors, UNC5A, UNC5B, and UNC5C, were also discovered as putative tumor suppressor genes in various tumors." (PMID 26207151, 2015). "The timing of molecular mutations in UNC5C and DCC was not random, with UNC5C inactivation occurring in early tumour lesions and DCC locus changes forming through progressive accumulation." (PMID 38546656, 2024). "Therefore, the NTN1/α6β4/UNC5C signalling pathway is critical for regulating tumour growth and metastasis." (PMID 38546656, 2024). "In addition, UNC5C is reported to be downregulated due to specific genetic alterations and inhibits apoptosis of tumor cells by suppressing proapoptotic signals." (PMID 32477968, 2020). "Interestingly, recent studies have demonstrated that DCC as well as UNC5C serve as dependence receptors for netrin-1, thus, reinforcing their potential role as tumor-suppressors in human cancers." (PMID 26207151, 2015). "Increased expression of TIMP1, MMP1, AGRN, UNC5A, and ADAMTS4 was observed, while the expression of UNC5C, TINAG, SPOCK3, and ITGA7 was reduced in the normal FHC cells compared to the HCT8 tumor cells." (PMID 39011483, 2024). "DPP7, CDR2L exhibited higher and UNC5C, RAB3B, SLC18A2, GPRASP1, PCDH9 exhibited lower expression in tumor tissues (P<0.05)." (PMID 37384293, 2023). "Other conditional tumor suppressor genes identified in CRC and other cancers, include DCC, UNC5C, p75NTR and MET." (PMID 23874207, 2013). "Their further research demonstrated that the timing of molecular mutations in UNC5C and DCC was not random, with UNC5C inactivation occurring in early tumour lesions and DCC locus changes forming through progressive accumulation." (PMID 38546656, 2024). "Because both DCC and UNC5C share the same netrin ligand and are colocalized in the gut, we hypothesized that solitary inactivation of either DCC or UNC5C may not be sufficient to promote tumor development in the stomach." (PMID 26207151, 2015).
cancer (13 papers, 2013 to 2025). A tumor composed of atypical neoplastic, often pleomorphic cells that invade other tissues. "Another mechanism underlying the loss of UNC5C in human cancers is represented by epigenetic alterations." (PMID 26207151, 2015). "For example, genes that encode DRs such as DCC, neogenin, UNC5B, UNC5C, or TrkC are repressed in multiple cancer types, while cancer cells can also escape DR‐mediated apoptosis through autocrine overexpression of ligands including DKK1, Netrin‐1, NT‐3, Sema3E, or HGF." (PMID 34542930, 2021). "The hot spot mutations Q491Kfs*15/Pfs*3 of UNC5C, which were both damaged in VEST3 and REVEL algorithms, occurred in seven patients with five cancers (STAD, UCEC, ACC, CESC, and ESCA), all of which were truncated mutations." (PMID 41407823, 2025). "The third netrin receptor (unc-5C) is also involved in cell proliferation and migration and is reduced in many cancers." (PMID 27716118, 2016). "UNC5A, UNC5B and UNC5C, which are the receptors of netrin 1, are all down-regulated in various cancers through promoter methylation." (PMID 26294325, 2015). "The gene expressions of netrin-1 dependence receptors, DCC and UNC5C, are frequently downregulated in many cancers." (PMID 26207151, 2015). "Forced YAP expression induced the expression of UNC5B and the related UNC5 family receptors, UNC5C and D, as well as their ligand NTN1/Netrin-1 in YAPoff cancers." (PMID 39172021, 2024). "Consistent with results obtained from the TCGA-COAD cohort, six CRGs, including DPP7, GPRASP1, UNC5C, RAB3B, PCDH9, SLC18A2, were significantly downregulated, whereas CDR2L was upregulated in cancer tissues in comparison with paracancerous normal tissues." (PMID 37384293, 2023). "In human cancer cells, enforced expression of UNC5A, UNC5B and UNC5C inhibits cell-anchorage growth and invasion in a way related to their pro-apoptotic activity." (PMID 33126652, 2020). "Meanwhile, UNC5C alterations gradually increased according to the progression of the TNM stage and were found in 2/11 (18 %) of stage I, 12 of 25 (48 %) of stage II, 19 of 30 (63 %) of stage III, and 7 of 11 (64 %) of stage IV cancers." (PMID 26207151, 2015). "Among the 40 cancers with UNC5C alterations, 10 cancers showed alterations both in terms of UNC5C methylation and 4q LOH, 13 cancers showed 4q LOH alone, and 17 cancers showed UNC5C methylation alone." (PMID 26207151, 2015). "Moreover, UNC5C and UNC5D transcripts remained undetectable upon OGT silencing (Decourcelle, A.; Dehennaut, V.; Université de Lille, CNRS, Inserm, CHU Lille, UMR9020-U1277—CANTHER—Cancer Heterogeneity, Plasticity and Resistance to Therapies, F-59000 Lille, France." (PMID 33126652, 2020).
infection (2 papers, 2017 to 2022). The state of being infected such as from the introduction of a foreign agent such as serum, vaccine, antigenic substance or organism. "We observed a slight increase in cell death upon UNC5C knockdown compared to cells transfected with a control siRNA, at late times post-infection (6 hpi)." (PMID 28394930, 2017). "Analysis of the effect of UNC5C knockdown on infection by other bacterial pathogens revealed a slight increase of Salmonella binding to cells treated with UNC5C siRNA (ca. 1.3-fold), which was reflected in a comparable increase of intracellular bacteria at 4 and 20 hpi." (PMID 28394930, 2017).
psychiatric disorder (1 paper, 2024). A disorder characterized by behavioral and/or psychological abnormalities, often accompanied by physical symptoms. "We propose, for the first time, an association between the UNC5C gene and psychiatric disorders, thereby expanding the understanding of genes related to psychiatric disorders." (PMID 38540364, 2024). "The NTN1/DCC signaling pathway, interacting with UNC5C, plays a crucial role in central nervous system axon guidance and has been associated with psychiatric disorders during adolescence in humans." (PMID 38540364, 2024). "Based on these findings, we are establishing, for the first time, an association between the UNC5C gene and psychiatric disorders." (PMID 38540364, 2024). "Whole-exome sequencing analysis unveiled two compound heterozygous causative mutations within the UNC5C gene in a patient diagnosed with psychiatric disorders." (PMID 38540364, 2024). "In the current study, we investigated a patient presenting with two compound heterozygous mutations in the UNC5C gene, hypothesizing that these mutations are causative of the diagnosed psychiatric disorders observed in the patient." (PMID 38540364, 2024). "Further research is required to validate the correlation of the UNC5C gene with psychiatric disorders, but we suggest including it in the genetic analysis of patients with psychiatric disorders." (PMID 38540364, 2024).
UNC5C also shares sentences with these, for which no sentence is quoted: neurodegenerative disease (3 papers); endometriosis (2); autism (1); autoimmune disease (1); cervical cancer (1); cervical neoplasms (1); coronary artery disease (1); diabetes (1); hippocampal atrophy (1); Huntington disease (1); insomnia (1); invasive carcinoma (1); lymph node metastasis (1); memory impairment (1); Parkinson’s (1); polyp (1); prostate (1); prostate carcinoma (1); proteinopathy (1); Stroke (1).